FOLR2 (folate receptor beta)
Diseases named in the same sentence as FOLR2 in open-access papers (continued):
Sharing a sentence is not in itself a finding about the gene and the disease.
gastric cancer (5 papers, 2019 to 2025). A primary or metastatic malignant neoplasm involving the stomach. "In conclusion, our study highlights the significant overexpression of FOLR1 and FOLR2 in gastric cancer and its association with adverse clinicopathological features, particularly for FOLR1." (PMID 38915965, 2024). "The statistical analysis demonstrated significant differences in the expression of FOLR1 and FOLR2 between the diffuse and intestinal histological types of gastric cancer." (PMID 38915965, 2024). "There is a lack of comprehensive studies investigating the roles of FOLR1 and FOLR2 in gastric cancer." (PMID 38915965, 2024). "While our study provides important insights into the expression and implications of FOLR1 and FOLR2 in gastric cancer, it has certain limitations." (PMID 38915965, 2024). "The high percentage of positivity for FOLR1 and FOLR2 expressions in gastric cancer tissues (82.76% and 70.69%, respectively) underscores the potential role of these receptors in gastric cancer biology." (PMID 38915965, 2024). "The study revealed high expression rates of FOLR1 and FOLR2 in gastric cancer tissues, at 48 (82.76%) and 41 (70.69%) respectively." (PMID 38915965, 2024). "Conversely, FOLR2 was significantly underexpressed in gastric cancer samples, with a fold change of 0.30." (PMID 38915965, 2024). "In this context, our study focused on the immunohistochemical expression of FOLR1 and FOLR2 in gastric cancer patients, aiming to elucidate their roles in the disease's pathogenesis and potential as prognostic markers or therapeutic targets." (PMID 38915965, 2024). "Our study objective was to evaluate the expression pattern of FOLR1 and FOLR2 in gastric cancer patients' tissue and blood specimens and correlate the results with the clinicopathological parameters." (PMID 38915965, 2024). "Overall, our findings support the idea that FOLR1 and FOLR2 could serve as potential targets for the development of novel therapies for gastric cancer." (PMID 38915965, 2024). "The underexpression of FOLR2 could reflect alterations in the tumor microenvironment or immune response dynamics in gastric cancer." (PMID 38915965, 2024). "During intestinal-type gastric cancer progression, epithelial cells trigger necroptosis in FOLR2+ macrophages via APP-TNFRSF21 signaling, resulting in a substantial depletion of FOLR2+ macrophages." (PMID 41267084, 2025). "The significant differences observed between the histological subtypes of gastric cancer, specifically diffuse and intestinal types, in relation to FOLR1 and FOLR2 expressions, align with the growing body of evidence that suggests molecular heterogeneity within gastric cancer subtypes." (PMID 38915965, 2024). "In a cohort of 58 gastric cancer patients, immunohistochemical analysis was used to assess the expression of FOLR1 and FOLR2 and correlate these findings with various clinical and pathological variables such as age, gender, cancer stage, tumor site, liver involvement, and histological type." (PMID 38915965, 2024).
non-small cell lung carcinoma (5 papers, 2020 to 2025). A group of at least three distinct histological types of lung cancer, including non-small cell squamous cell carcinoma, adenocarcinoma, and large cell carcinoma. "A previous study reported that folate receptor-beta (FRβ) is highly expressed in non-small-cell lung cancer on tumor tissues." (PMID 40006612, 2025).
osteoarthritis (5 papers, 2019 to 2026). A noninflammatory degenerative joint disease occurring chiefly in older persons, characterized by degeneration of the articular cartilage, hypertrophy of bone at the margins and changes in the synovial membrane. "FOLR2 plays a role in the regulation of folate receptors, and folate receptors have a great relationship with macrophages in the synovial membrane of osteoarthritis." (PMID 31781601, 2019).
colorectal cancer (3 papers, 2015 to 2022). A primary or metastatic malignant neoplasm that affects the colon or rectum. "Despite the existence of multiple well-characterized colorectal-cancer-associated macrophage subgroups, including C1QC+ TAMs, SPP1+ TAMs, and FCN1+ TAMs, we identified a kind of tumor-resident FOLR2+ LYVE1+ macrophage subgroup in colorectal cancer." (PMID 36172359, 2022). "The existence and function of two states of exhausted CD8+ T (Tex) subtypes in colorectal cancer, and FOLR2+ LYVE1+ macrophages indicating unfavorable prognosis in colorectal cancer were identified and validated." (PMID 36172359, 2022). "By integrating scRNA-seq data, immunofluorescent staining, and TCGA datasets, we identified that FOLR2+LYVE1+ macrophages in colorectal cancers, and exhibited steady-state macrophage transcriptional profile and moderate-to-low energy metabolic features." (PMID 36172359, 2022). "However, the status and function of FOLR2+ macrophages in colorectal cancer are poorly characterized." (PMID 36172359, 2022).
colorectal tumor (3 papers, 2015 to 2022). "We presume that the diminished expression of FOLR2 in colorectal tumours can contribute to the declined methyl-donor availability, which may lead to the process of global DNA hypomethylation." (PMID 35655145, 2022).
osteosarcoma (3 papers, 2019 to 2021). A usually aggressive malignant bone-forming mesenchymal neoplasm, predominantly affecting adolescents and young adults. "We showed that the transcript for the cellular receptor for folic acid uptake, folate receptor beta (FOLR2), is upregulated in osteosarcoma exposed to MAP." (PMID 32655131, 2020).
prostate carcinoma (3 papers, 2024 to 2026). A carcinoma that arises from epithelial cells of the prostate gland. "Androgen deprivation therapy (ADT) induces the accumulation of TAMs around blood vessels and increases the expression of markers of a protumor phenotype, including folate receptor-beta (FR-β), MRC1 (CD206), CD169 and VISTA, in PvTAMs in human and mouse prostate cancers." (PMID 39516356, 2024).
bladder cancer (2 papers, 2021 to 2022). "Few studies had reported that the six genes (TBXAS1, GYPC, HPGDS, GAB3, ADORA3, and FOLR2) had strong correlation with bladder cancer." (PMID 36275756, 2022).
endometriosis (2 papers, 2022 to 2024). The growth of functional endometrial tissue in anatomic sites outside the uterine body. "To begin to ascertain whether the TAM-like macrophages identified in the scRNA-Seq dataset exhibited prodisease properties in line with their transcriptional phenotype, we FACS sorted Folr2+ macrophages from the peritoneal lavage and lesions of mice with experimentally induced endometriosis." (PMID 39255000, 2024). "TAM-like macrophages also exhibited restricted and elevated expression of Folr2, a reliable marker induced in both lesion-resident TAM-like macrophages and some peritoneal macrophages of mice with endometriosis." (PMID 39255000, 2024).
gastric adenocarcinoma (2 papers, 2021 to 2024). "To decipher the cellular state and function of macrophages in the process of intestinal-type gastric adenocarcinoma carcinogenesis, we reclustered all of the macrophages into five clusters, including macrophage_IL1B, macrophage_CHI3L1, macrophage_CXCL3, macrophage_IFIT3 and macrophage_FOLR2." (PMID 39702278, 2024).
ovarian tumor (2 papers, 2020 to 2024). "The transcriptomic analysis shows that the human ovarian tumor cells SKOV3 and OVCAR3 expressed the FOLR1 isoform and that the different isolated immune cells expressed the FOLR2 isoform." (PMID 32326210, 2020).
chronic gastritis (1 paper, 2024). Inflammation of the stomach that is chronic in nature. "mIHC revealed that FOLR2+ macrophages (CD68+FOLR2+) were enriched in nonatrophic chronic gastritis (NAG) and CIM." (PMID 39702278, 2024).
Cirrhosis (1 paper, 2023). A chronic disorder of the liver in which liver tissue becomes scarred and is partially replaced by regenerative nodules and fibrotic tissue resulting in loss of liver function. "Our results showed that several crucial drivers, including regulators that are potentially associated with the progression of cirrhosis, such as SLC40A1, DAB2, FOLR2, GPAT3, and CDA, were upregulated during fibrosis." (PMID 36845083, 2023).
Granuloma (1 paper, 2023). A compact, organized collection of mature mononuclear phagocytes, which may be but is not necessarily accompanied by accessory features such as necrosis. "However, while it is still uncertain if such a phenotype is present in CS, there has been a report that CS granulomas tend to express Folate Receptor-β (FOLR2) which has been recently implicated in alternative activation polarization in cardiac MΦ." (PMID 37576111, 2023).
head and neck squamous cell carcinoma (1 paper, 2024). A squamous cell carcinoma that arises from any of the following anatomic sites: lip and oral cavity, nasal cavity, paranasal sinuses, pharynx, larynx, and salivary glands. "In head and neck squamous cell carcinoma (HNSCC), SPP1+CCL18+ and SPP1+FOLR2+ tumor-associated macrophages (TAMs) harbored pro-angiogenic and metastatic transcriptional programs and were correlated with poor survival." (PMID 39409192, 2024).
interstitial lung disease (1 paper, 2024). A diverse group of lung diseases that affect the lung parenchyma. "The role of FOLR2-Mφ has been overlooked in previous scRNA-seq studies of interstitial lung disease and their status in IPF remains poorly characterized." (PMID 38896611, 2024).
neuroborreliosis (1 paper, 2019). "Moreover, we propose that the overexpressed FOLR2 which was demonstrated by the real-time PCR and western blotting could play a key role in neuroinflammation of the neuroborreliosis based on PPI analysis for the first time." (PMID 31316336, 2019). "Transcriptome results obtained from the interaction of Bb with the CNS indicate that FOLR2 could be involved in the pathogenesis of neurological Lyme disease, however, to our knowledge FOLR2 is not yet reported in Bb- induced infection." (PMID 31316336, 2019).
renal fibrosis (1 paper, 2024). A final common manifestation of a wide variety of chronic kidney diseases characterized by glomerulosclerosis and tubulointerstitial fibrosis. "If the role of macrophages is well-established in renal fibrosis, the role of FOLR2+ macrophages is not known." (PMID 38272907, 2024).
tumor (172 papers, 2011 to 2026). "The most abundant lesion-resident population was LRM4 which was characterized by expression of Ccl8, Mrc1, Gas6, Marks, Cbr, and Folr2, a signature shared with many tumor-associated macrophages (TAM) (19, –21)." (PMID 39255000, 2024). "To test the association between FOLR2 + macrophage abundance and clinical outcome, we also analyzed whole-tumor transcriptome data from the KM plotter database." (PMID 39702278, 2024). "Folate receptor beta (FRβ), which was usually overexpressed in M2 tumor-associated macrophages (TAMs) and NSCLC cells, was associated with the poor prognosis of NSCLC patients." (PMID 35164213, 2022). "FOLR2 encodes the folate receptor 2 protein and is known to be overexpressed in tumor-associated macrophages." (PMID 33968133, 2021). "FOLR2 encodes the gene product folate receptor beta and has been shown to be expressed on the M2 phenotype of tumor associated macrophages, or TAMs." (PMID 25971554, 2015). "In addition to tissue remodeling, LYVE‐1+ macrophages, also marked by TIM4 and FOLR2, are also associated with immune regulation in the tumor microenvironment." (PMID 38426622, 2024). "Indeed, Detox-iCAF, IL-iCAF and IFNγ-iCAF recruit monocytes and induce a FOLR2+ tumor-associated macrophage (TAM) phenotype, while ECM-myCAF and TGFβ-myCAF promote TREM2+ TAM and NKG2A+ regulatory NK phenotypes." (PMID 38561380, 2024). "More specifically, FOLR2 expression has been found to strongly correlate with the expression of M-MØ-specific genes in tissue-resident macrophages, tumor-associated macrophages (TAM) and macrophages from inflamed synovium, and also correlates with the presence of the PU.1 transcription factor." (PMID 32532019, 2020). "Notably, a higher density of FOLR2+ macrophages within tumors is associated with improved patient survival, highlighting their potential as prognostic markers and their role in facilitating anti-tumor immune responses." (PMID 40083710, 2025). "However, an off-label use may be identifying tumor associated macrophages because they express folate receptor beta and would also endocytose this new contrast agent." (PMID 36494869, 2022). "Tumour-associated macrophages (TAMs) originate from both FCN1+ monocytes and FOLR2+ tissue-resident macrophages, displaying two polarisation states with distinct prognostic associations." (PMID 41636115, 2026). "In clear cell renal cell carcinoma, IL-1β+ and IL-18+ Tregs co-localize with MRC1+FOLR2+ TAMs at tumor-normal interfaces, forming a positive feedback loop that sustains synergistic pro-tumor effects." (PMID 41417432, 2025). "FOLR2-expressing macrophages have been reported as a subpopulation with controversial functions in the tumor microenvironment." (PMID 40530387, 2025). "Using the GSVA algorithm, SPP1+ macrophages were found to be significantly increased in tumor tissues, while FOLR2+ macrophages were enriched in adjacent normal tissues." (PMID 40666097, 2025). "For example, ECM-myCAF, IFNαβ-myCAF, and TGFβ-myCAF clusters co-localize with immune cells such as TREM2+ tumor-associated macrophages (TAM) and SPP1+ TAM within the tumor bed, while Detox-iCAF co-localizes with FOLR2+ TAM in immuno-protective niches." (PMID 40890855, 2025). "In contrast, in HCC, FOLR2+ macrophages exhibited a fetal-like reprogramming that enhanced the immune-suppressive state in tumor tissues, similar to the immune characteristics observed during liver development." (PMID 40376263, 2025). "Monocyte-derived TAMs, for example, TREM2+ TAMs, infiltrate the tumor core, whereas tissue-resident-derived TAMs, such as FOLR2+ TAMs, are predominantly located within the perivascular niche of the tumor stroma." (PMID 40427136, 2025). "Incorporating folic acid into the complex with the API and carrier ensures specific, targeted interaction with tumor cells, due to the expression of folate receptor beta (FR-α,-β), including on cancer cells." (PMID 40843729, 2025).
tumor (continued). "Multiple studies have demonstrated that FOLR2+ TAMs play a key role in tumor initiation and progression, especially in regulating immune responses." (PMID 40376263, 2025). "FOLR2+ macrophages were identified in perivascular regions of the tumor stroma and their infiltration correlates with better patient survival." (PMID 38717149, 2024). "Several types of tumor-associated macrophages (TAM), such as FOLR2+ (Folate receptor beta) and TREM2+ (Triggering receptor expressed on myeloid cells 2) TAM have been identified." (PMID 38272907, 2024). "In recent years, studies have mainly focused on FOLR2+ macrophages in the tumor microenvironment and their role in immunotherapy." (PMID 38166756, 2024). "TREM2, FOLR2, and CD163 are all markers found on tumor-associated M2 macrophages in adult cancer and have been shown to suppress the immune response and promote tumor growth." (PMID 38358826, 2024). "In mice with experimentally induced endometriosis, FOLR2+ macrophages exhibit proangiogenic and profibrotic activity, which, in the case of cancer, support tumor growth." (PMID 39516356, 2024). "Research involving CAR-T cells targeting folate receptor beta (FRβ) in tumor treatments has shown promising results, with potential improvements in tumor control and survival." (PMID 39068459, 2024). "Monocyte-derived (mo)TAM (for example TREM2+ TAM) infiltrate the tumour core, whereas tissue-resident-derived TAMs (such as FOLR2+ TAM) are predominately located within the perivascular niche of the tumour stroma." (PMID 39430099, 2024). "For instance, FOLR2+ macrophages have been shown to interact with CD8+ T cells to enhance the anti-tumor immune response." (PMID 39202452, 2024). "Microscopic analysis demonstrated that positive expression of FOLR1 and FOLR2 proteins in tumor cells was present in 48 (82.76%) and 41 (70.69%) out of 58 patients, respectively." (PMID 38915965, 2024). "Specifically, FOLR2 + macrophages, located near blood vessels within the tumor stroma, have been observed aggregating with CD8 + T cell clusters." (PMID 39068459, 2024). "FOLR2+ TAM were either detected in the Wound-myCAF-enriched intra-tumor stroma or retained at the invasive margin." (PMID 38561380, 2024). "We sorted Macro CD5L+ (CD45+ F4/80+ FOLR2+) in the tumor environment of orthotopic injection model and injected the sorted Macro CD5L+ into the subcutaneous iCCA model to directly explore its effect on GOLP therapy." (PMID 38245530, 2024). "Since miR-622 upregulated cell cycle to promote tumor growth, we further verified correlation between FOLR2 and cell cycle process." (PMID 38166756, 2024). "FOLR2+ macrophages are located in the stroma in perivascular niches and interact with tumor-infiltrating CD8+ T cells, which is positively correlated with CD8+ T-cell activation and patient survival." (PMID 39516356, 2024). "Compared to normal tissues, the tumor group exhibited a higher abundance of Macro-FOLR2, Macro-SPP1 and cDC-FCER1A, with a lower proportion of Mono-FCN1." (PMID 39093451, 2024). "The results indicated an increase in MS4A4A, HLA‐DMB, LY86, MS4A7, and FOLR2 expression in GBM tumor samples compared to normal tissue samples (n = 706)." (PMID 38997808, 2024). "FOLR2+ TAMs reside in a perivascular niche within the tumor stroma and secrete pro-angiogenic cytokines such as TGF-β and VEGF." (PMID 38068740, 2023). "We found that SPP1 TAMs reside in hypoxic and necrotic tumor regions, and a novel subset of FOLR2 tissue resident macrophages (TRMs) supports the plasma cell tissue niche." (PMID 36711732, 2023). "By contrast, other cell types beyond the tumor boundary, such as B cells, Macro-FOLR2, Myofib, and Fib-SFRP2, exhibited weak interactions in the tumor boundary niche." (PMID 36806082, 2023). "According to spatial analyses, TREM2+ macrophages are inside the tumor nest and close to the invasive margin, whereas FOLR2+ macrophages reside away from the tumor nest and remain in the perivascular area." (PMID 37822933, 2023).